ASCL1 (achaete-scute family bHLH transcription factor 1)
Diseases named in the same sentence as ASCL1 in open-access papers (continued):
Sharing a sentence is not in itself a finding about the gene and the disease.
glioblastoma (36 papers, 2014 to 2025). The most malignant astrocytic tumor (WHO grade IV). "Loss of ASCL1 in glioblastoma stem cells reduces their proliferation in vitro and, to a lesser extent, in vivo in mice, where Ascl1 works redundantly with the bHLH TF Olig2 to sustain tumour growth." (PMID 40527452, 2025). "In murine glioblastoma models, loss of ASCL1 significantly reduces glioblastoma growth rate and extents animal survival." (PMID 35456993, 2022). "For instance, in glioblastoma, under low ASCL1 conditions, the FZD4–LRP5–TSPAN12 complex stimulates Wnt/β-catenin signaling." (PMID 41357583, 2025). "On the other hand, high ASCL1 expression promotes differentiation of glioblastoma stem cells into neurons and promotes tumour cell migration in vivo." (PMID 40527452, 2025). "Glioblastomas respond to overexpression of ASCL1 by terminally differentiating proliferating cells, thus restricting tumor expansion." (PMID 36931659, 2023). "Neurog2 and ASCL1, both basic helix loop helix (bHLH) transcription factors, have been shown to reprogram glioblastoma cells into neuron-like cells." (PMID 37582760, 2023). "The transcriptomic analysis also revealed that GZ17-6.02 treatment results in suppression of several genes implicated in glioblastoma growth and invasion, such as EGR1, ASCL1, CD109, ABCG2, and CDH5." (PMID 35456993, 2022). "Taken together, our findings lead to a model that suggests that phosphorylation of the developmental master-regulator ASCL1 plays a pivotal role in controlling differentiation of at least a subset of glioblastoma stem cells." (PMID 35149717, 2022). "In comparison, the level of ASCL1 overexpression achieved by inhibition of the NOTCH signalling pathway in glioblastoma cells is between 1.5–2.5 fold." (PMID 35366798, 2022). "Consistent with their developmental functions, our transcriptome results showed that Ascl1 and Neurog2 elicited different neurogenic programs in human glioblastoma cells." (PMID 33755378, 2021). "We found that expression of TLX and ASCL1 (human counterparts of Tll and Asense) are also mutually exclusive in glioblastoma, suggesting a potentially conserved route to tumourigenesis." (PMID 32073402, 2020). "Based on our results, we would predict that glioblastoma cells with high levels of TLX would exhibit low ASCL1 expression." (PMID 32073402, 2020). "Ectopic expression of ASCL1 in glioblastoma stem cells was sufficient to promote neuronal differentiation." (PMID 32073402, 2020). "Intriguingly, ASCL1 levels also vary between human glioblastoma samples and low levels are correlated with shorter survival time." (PMID 32073402, 2020). "To determine if TLX and ASCL1 expression are mutually exclusive in glioblastoma, we analysed a previously published single-cell RNA sequencing (scRNA seq) data set that profiled glioblastoma samples from 28 patients, including both adult and pediatric tumours." (PMID 32073402, 2020). "Our results predict that expression of TLX and ASCL1 should be mutually exclusive in glioblastoma, which was verified in single-cell RNA-seq of human glioblastoma samples." (PMID 32073402, 2020). "Ectopic expression of ASCL1 in adult glioblastoma cells induces features of neuronal maturation and inhibition of glial cell differentiation." (PMID 32142668, 2020). "ASCL1 has well-described pro-neural functions, and enhanced ASCL1 expression can impair adult glioblastoma tumorigenicity by promoting neuronal-like differentiation." (PMID 32142668, 2020). "ASCL1-mediated inhibition of DKK1 consequently leads to activation of Wnt signaling, and ASCL1 was found to be crucial for glioblastoma CSC maintenance and tumorigenicity." (PMID 28148257, 2017). "In view of the devastating effect of stroke and glioblastoma and the dismal paucity of therapeutic options for these conditions, this Ascl1-based strategy should be worth further exploration." (PMID 28832532, 2017).
glioblastoma (continued). "In another very recent report, Dirk’s laboratory investigated the molecular stratification of patient-derived glioblastoma cell types, and noted that a subset of glioblastoma stem cells (GSCs) have high levels of Ascl1." (PMID 28832532, 2017). "For example, MYCN is a target gene of ASCL1 in glioblastoma." (PMID 40498845, 2025). "In particular, ASCL1 has been shown to recognize its neuronal targets in a closed chromatin state when overexpressed in fibroblasts (initiating neuronal reprogramming), undifferentiated neural stem cells, and glioblastoma stem cells." (PMID 36931659, 2023). "Furthermore, upregulating ASCL1 levels by NOTCH inhibition has been shown to differentiate glioblastoma stem cells to a neuronal fate." (PMID 35366798, 2022). "The increase in NeuN expression suggested that Ascl1SA6 might have an enhanced capacity to induce neuronal differentiation compared to Ascl1, as shown in the embryonic cortex and in glioblastoma cells." (PMID 36061596, 2022). "To identify the underlying mechanism of the glioblastoma cell-to-neuron conversion process, we performed RNA-sequencing (RNA-seq) and transcriptome analyses of GBM cells after Neurog2 or Ascl1 overexpression, with GFP alone serving as the control group (3 replicates for each group)." (PMID 33755378, 2021). "However, when we compared TLX and ASCL1 expression within the malignant population, we found very few cells that expressed both transcripts, suggesting that TLX and ASCL1 are indeed mutually exclusive in malignant glioblastoma cells." (PMID 32073402, 2020). "Moreover, ectopic ASCL1 expression in adult glioblastoma inhibits some aspects of glial differentiation." (PMID 32142668, 2020). "Furthermore, a recent study demonstrated that low expression levels of ASCL1 correlate with glioblastoma malignancy." (PMID 32073402, 2020). "Intriguingly, the impairment of Notch signaling in secondary Glioblastoma, in which Hes1 expression is almost absent, is associated with the overexpression of ASCL1." (PMID 30832246, 2019). "On the other hand, the activation of Notch signaling in primary Glioblastoma is associated with low levels of ASCL1, suggesting that Notch inhibition via ASCL1 upregulation might be responsible for a potential progression into secondary Glioblastomas." (PMID 30832246, 2019). "However, ASCL1 has recently been shown to play a functional role in maintaining ‘stemness’ in murine cortical neural stem cells and in human glioblastoma, indicating that ASCL1 expression does not always result in neuronal differentiation." (PMID 25786414, 2015). "In our study, NeuroD4 successfully reprogrammed U251 and KNS89 glioblastoma cell lines into a neural differentiation state, achieving an efficiency of over 90%, which is comparable to the reprogramming efficiency achieved by overexpressing ASCL1 or knocking down PTBP1." (PMID 37582760, 2023). "In addition, it was recently demonstrated that ASCL1SA5 (note that the human ASCL1 gene has 5 SP sites) can induce a glioblastoma stem cell line to undergo terminal differentiation and exit the cell cycle more effectively than native ASCL1, leading to growth suppression of this tumor cell line." (PMID 36061596, 2022). "Importantly, force-expression of Ascl1 was shown to drive proliferative reactive astroglia formed during stroke and glioblastoma stem cells towards neuronal differentiation, and this could potentially diminish CNS damage resulting from their proliferation." (PMID 28832532, 2017). "In glioblastoma cancer stem cells (GBM CSCs), Ascl1 has been shown to bind a site near the Wnt antagonist gene Dkk1, whose regulation mediates Ascl1 activity in these cells." (PMID 25189209, 2014). "Transcription factors like ASCL1, HES1, OLIG2, SOX2, and NOTCH-ligands (DLL1/3) play crucial roles in GBM plasticity by maintaining a pool of quiescent glioblastoma stem cells (GSCs)." (PMID 40358199, 2025).
glioblastoma (continued). "For instance, ASCL1 has been shown to be critical in maintaining “stemness” in human glioblastoma, and when upregulated by NOTCH inhibition, ASCL1 promoted glioblastoma cell differentiation into a neuronal lineage attenuating its tumorigenicity." (PMID 35366798, 2022). "ASCL1 phosphorylation and ID2 upregulation are roadblocks to glioblastoma stem cell differentiation." (PMID 36147490, 2022). "ASCL1 is a gene classifier for the pro-neural (PN) transcriptional subgroup of GBM, which plays as a relevant role in the neuronal-like differentiation of glioblastoma stem cells (GSCs)." (PMID 36147490, 2022). "Analysis of scRNA seq from glioblastoma revealed that TLX and ASCL1 expression is mutually exclusive." (PMID 32073402, 2020). "Achaete-scute homolog 1 gene (ASCL1) is a gene classifier for the proneural (PN) transcriptional subgroup of glioblastoma (GBM) that has a relevant role in the neuronal-like differentiation of GBM cancer stem cells (CSCs) through the activation of a PN gene signature." (PMID 30538287, 2019). "In glioblastoma, downregulation of TCF3 by ASCL1 is essential for the maintenance and in vivo tumorigenicity of glioblastoma CSCs." (PMID 29299140, 2017). "ASCL1 has been shown to promote WNT signalling by directly repressing DKK1, a negative regulator of WNT signalling, and synergising with WNT3A to induce active WNT signalling in glioblastoma stem cells." (PMID 41287940, 2025). "In glioblastoma (GBM), the most common and aggressive malignant primary brain tumor, belongs to the family of astrocytic tumors, elevated NDP expression was significantly associated with prolonged survival, especially in patients with low ASCL1 expression levels." (PMID 41357583, 2025). "ASCL1 and OLIG2 are two basic-helix-loop-helix transcription factors that are highly co-expressed in glioblastoma (GBM)." (PMID 39609428, 2024). "In glioblastoma, for example, phospho-mutant ASCL1 could not produce fully mature neurons, in part because of the upregulation of ID proteins that can negatively feedback on ASCL1 activity." (PMID 40527452, 2025). "Importantly, forced ASCL1 in the mesenchymal subtype does not drive neuronal differentiation, but instead induces a neuroendocrine phenotype coupled with increased malignancy, which has important clinical implications for developing safe and effective interventions for glioblastoma." (PMID 40527452, 2025).
prostate carcinoma (32 papers, 2009 to 2025). A carcinoma that arises from epithelial cells of the prostate gland. "Knockout of TFAP4 was found to decrease ASCL1/2 expression, inhibiting cell growth in ASCL1+ prostate cancer cells but causing a drastic increase in ASCL2+ cells." (PMID 39372390, 2024). "Altered expression of key regulators of cell fate and lineage commitment have been associated with NE transdifferentiation in prostate cancer, including ASCL1 and REST." (PMID 31836808, 2019). "Overall, these data point to distinct epigenetic mechanisms of dysregulation of key prostate cancer biomarkers (GSTP1) including NE (ASCL1, SEZ6L), and luminal (e.g FOLH1) genes." (PMID 40593552, 2025). "Given the well‐established role of oncogenic transcription factors such as AR and ASCL1 in driving prostate cancer, our investigation extended to evaluating the contribution of novel lineage‐related TFs to cell growth and aggressiveness." (PMID 40091506, 2025). "This is in stark contrast to prostate cancer in which ASCL1 promotes lineage plasticity and treatment resistance." (PMID 39874041, 2025). "The regulation of Bcl-2 expression in prostate cancer is complex and involves mechanisms such as DNA methylation and the influence of lineage plasticity factors like ASCL1 (Achaete-scute homolog 1)." (PMID 40841912, 2025). "Recent studies have identified corresponding subtypes in SCN prostate cancer, including ASCL1, POU2F3/ASCL2, and NEUROD1 (8, –10)." (PMID 39589879, 2024). "In closing, we report a robust, scalable platform for studying lineage plasticity in a format amenable to deep molecular interrogation and perturbation and identify Ascl1 as a critical gatekeeper of NE transformation and tumor heterogeneity in prostate cancer." (PMID 39394434, 2024). "Overall, these data further support the importance of the NOTCH/ASCL1 signaling axis as a critical determinant of NE differentiation in prostate cancer." (PMID 39024561, 2024). "ASCL1 mediate terminal neuroendocrine differentiation of prostate cancer by regulating lineage-determinant transcription factor FOXA2." (PMID 39470735, 2024). "Targeting ASCL1 can effectively change the phenotype of prostate cancer and mitigate drug resistance." (PMID 38726001, 2024). "Mechanistic studies have revealed that ASCL1 can promote cAMP-response element binding protein (CREB) expression in prostate cancer." (PMID 38726001, 2024). "ASCL1 can promote progression of castration-resistant prostate cancer to neurosecretory prostate cancer by mediating ferroptosis resistance." (PMID 37980165, 2023). "The link between ASCL1 and the development of stem cell and neuronal phenotypes was confirmed, for example, in studies targeting prostate cancer." (PMID 37783914, 2023). "Strong positive correlation exists between induction of ASCL1 expression and acquisition of NE markers in prostate cancer following androgen deprivation, whilst prostate cancer NE transdifferentiation is facilitated by loss of REST13." (PMID 31836808, 2019). "Temporal and spatial changes in ASCL1 expression also correlate with transdifferentiation of prostate cancer cells." (PMID 31836808, 2019). "ASCL1-mediated reprogramming to neurons has mainly used fibroblasts and glia as the cells of origin, but has also been demonstrated in hepatocytes, blood mononuclear cells, T cells and prostate cancer cells." (PMID 40527452, 2025). "Previous studies have demonstrated that ASCL1 reprograms prostate cancer by remodeling chromatin." (PMID 38726001, 2024). "Based on these results, ASCL1 might be an important factor in establishing the NE lineage identity in prostate cancer." (PMID 35477723, 2022). "ASCL1 was recently involved in neuroendocrine differentiation also in prostate cancer." (PMID 23114535, 2012).
prostate carcinoma (continued). "Moreover, further understanding of ASCL1 role in balancing cell fate decisions in different cellular contexts will be essential also to establish ASCL1 pathogenic role in neurological cancers, and in other non-neural cancers, such as lung and prostate cancer." (PMID 40527452, 2025). "Genes such as ASCL1, WDFY4, GLYATL2, and EDIL3, which are upregulated in CRPC, likely drive the progression from primary prostate cancer to CRPC." (PMID 40165961, 2025). "ASCL1 and ASCL2 are mutually exclusive during NEtD in prostate cancer, similar with the relationship between MYCL and MYC in SCLC and FOXA2 and FOXA1 in NEPC." (PMID 39372390, 2024). "We analyzed ASCL1 ChIP-Seq datasets from SCN lung and prostate cancer cell lines, as well as in LuCaP prostate cancer patient-derived xenografts (PDXs)." (PMID 39589879, 2024). "In NE prostate cancer, a novel molecular subtype of prostate cancer has been identified, consisting of class I (ASCL2+) and class II (ASCL1+) types." (PMID 39372390, 2024). "The expression of ASCL1, FOXA2, and PROX1 positively correlated in prostate cancer patient datasets as well as lung cancer." (PMID 39470735, 2024). "In prostate cancer, POU2F3 expression is observed in both CRPC and NEPC, and it appears to be mutually exclusive with ASCL1." (PMID 39372390, 2024). "This alteration of EZH2 activity by ASCL1 was not unique to prostate cancer, but seems like a common effect of ASCL1 as observed in lung adenocarcinoma and SCLC." (PMID 35477723, 2022). "By contrast, ASCL1 is not expressed in prostate cancer until initiation of the NE fate transition." (PMID 39394434, 2024). "Though up to now SOX11 has not been found to be the downstream of ASCL1 in pulmonary NE cell differentiation, NE differentiation of prostate cancer cells is suggested to be partially mediated by SOX11, and a recent paper shows that SOX11 mRNA is upregulated in pulmonary HG-NECs." (PMID 34996493, 2022). "Interestingly, ASCL1 and NEUROD1 also regulate different genes that commonly contribute to neuronal function in pulmonary neuroendocrine tumors, a phenomenon which may also occur in prostate cancer." (PMID 33572108, 2021).